TWIST1 (twist family bHLH transcription factor 1)
Diseases named in the same sentence as TWIST1 in open-access papers (continued):
Sharing a sentence is not in itself a finding about the gene and the disease.
invasive breast carcinoma (6 papers, 2012 to 2022). A carcinoma that infiltrates the breast parenchyma. "The over-expression of full-length Anxa2 increased the expression of three EMT-TFs such as SLUG, SIP1 and TWIST1 and two MMPs (MMP2, MMP9) in invasive breast cancer MDA-MB-231 cells." (PMID 32244350, 2020). "Over-expression of Anxa2 in invasive breast cancer MDA-MB-231 cells accelerated NF-κB activation and the expression EMT-TFs including SLUG, SIP1 and TWIST1, followed by the down-regulation of E-cadherin and up-regulation of N-cadherin." (PMID 32244350, 2020).
invasive lobular carcinomas (6 papers, 2011 to 2021). "In summary, we have found that the TWIST1 mRNA expression level is associated with small tumor size, invasive lobular carcinoma, stromal-rich tumors and with PGR and ERBB2 (over)expression." (PMID 22967435, 2012). "An inverse correlation between the expression levels of Twist1 and E-cadherin has been observed in human invasive lobular carcinomas." (PMID 27074574, 2016). "This corroborated a previous study in which the TWIST1 promoter was much less frequently methylated in invasive lobular carcinomas than in invasive ductal carcinomas." (PMID 21464926, 2011). "In BC, a high level of Twist1 expression is more common in invasive lobular carcinomas." (PMID 23815808, 2013). "Furthermore, TWIST1 mRNA expression was higher in invasive lobular carcinoma (ILC) compared with invasive ductal carcinoma (IDC)." (PMID 22967435, 2012). "Moreover, significant correlation was found between the expression of TWIST1 and the appearance of invasive lobular carcinomas." (PMID 21464926, 2011).
lymphoma (6 papers, 2015 to 2025). A malignant (clonal) proliferation of B- lymphocytes or T- lymphocytes which involves the lymph nodes, bone marrow and/or extranodal sites. "In the current study, we demonstrated that the in vitro anti-lymphoma potential of erufosine is diminished by TWIST1 expression and micellar curcumin substantially increases its antineoplastic activity." (PMID 36559182, 2022). "The anti-lymphoma effect of ERF in CTCL cell lines was dependent on the TWIST1 expression." (PMID 36559182, 2022).
myelodysplastic syndrome (6 papers, 2015 to 2023). A clonal hematopoietic disorder characterized by dysplasia and ineffective hematopoiesis in one or more of the hematopoietic cell lines. "TWIST1 expression is highly upregulated in malignant HSCs from Myelodysplastic syndrome (MDS) patients, with its expression increasing with more advanced disease." (PMID 37600794, 2023). "TWIST-1 has also been reported as an antiapoptotic factor in myelodysplastic syndromes (MDS)." (PMID 26023795, 2015). "On the other hand, TWIST1 is shown to enhance the expression of miR-10a in CD34+ cells in myelodysplastic syndrome, and TWIST1/miR-10a-axis could be used as a therapeutic target in the treatment of the myelodysplastic syndrome." (PMID 36555120, 2022).
acute myeloid leukemia (5 papers, 2015 to 2025). Acute myeloid leukemia (AML) is a group of neoplasms arising from precursor cells committed to the myeloid cell-line differentiation. "Our study shows that TWIST-1 is overexpressed in bone marrow mononuclear cells of patients with acute myeloid leukemia (AML) and chronic myeloid leukemia (CML)." (PMID 26023795, 2015). "Knowing that Bmi1 expression is essential for maintenance of leukemic stem cells, we speculate that Twist1 might govern the pathogenesis of acute myeloid leukemia (AML) development as well." (PMID 26832848, 2015). "TWIST1, a transcription factor, is central to the pathophysiology of acute myeloid leukemia (AML), affecting multiple biological processes that govern disease progression and treatment response." (PMID 39200378, 2024).
medulloblastoma (5 papers, 2011 to 2023). A malignant, invasive embryonal neoplasm arising from the cerebellum. "TWIST1 was also associated with both metastasis at diagnosis and relapse in medulloblastoma patients." (PMID 33948561, 2021). "In conclusion, we identified a role for TWIST1 during medulloblastoma metastasis and demonstrate the potential of therapeutically inhibiting ABCB1 with the FDA-approved vardenafil to prevent metastasis." (PMID 33948561, 2021). "We knocked down TWIST1 using shRNA and degraded TWIST1 protein chemically using Harmine, allowing for further investigation of the functional importance of TWIST1 in medulloblastoma cell migration." (PMID 33948561, 2021). "To this end, we assessed the role of the EMT transcription factor, TWIST1 in medulloblastoma cell migration." (PMID 33948561, 2021). "TWIST1 protein expression was then assessed in a TMA of 70 medulloblastoma patients from Nottingham and Birmingham hospitals." (PMID 33948561, 2021). "TWIST1-silenced medulloblastoma cells present reduced BMI1 expression, while BMI1-silenced medulloblastoma cells present similar levels of TWIST1 expression as compared with control." (PMID 30297829, 2018). "Our findings suggest that NOTCH1-induced medulloblastoma metastasis occurs through TWIST1-induced BMI1 activation." (PMID 30297829, 2018). "Here we show that loss of TWIST1 resulted in reduced BMI1 expression and inhibition of Group 3 medulloblastoma metastasis." (PMID 30297829, 2018). "Here, the authors show that in Group 3 medulloblastoma NOTCH1 activates BMI1 through the activation of TWIST1, driving metastasis and self-renewal, and in mouse models a NOTCH1 blocking antibody decreased spinal metastases." (PMID 30297829, 2018). "Our work provides evidence that ABCB1 inhibition could provide a promising therapeutic strategy to target TWIST1-induced metastasis in medulloblastoma." (PMID 33948561, 2021). "TWIST1 was exclusively expressed in aggregating cell lines in an in vitro model of medulloblastoma metastasis and at the migratory edge of an in vivo metastatic medulloblastoma model." (PMID 33948561, 2021). "This supports our hypothesis that, in common with several other types of cancer, TWIST1 is a master regulator of tumor metastasis in medulloblastoma." (PMID 33948561, 2021). "In these cells, the gene and signaling pathways that are common to several medulloblastoma lineages have been identified, such as NRP1, MSI1, TWIST1, MYCN, and OX2." (PMID 36982406, 2023). "On the other hand, both TWIST1- and BMI1-silenced medulloblastoma cells present similar levels of NICD1 expression as compared with control, suggesting that NOTCH1 is upstream of TWIST1 and BMI1." (PMID 30297829, 2018). "Together, these findings indicate that the NOTCH1-induced TWIST1 activation contributes to the activation of BMI1, therefore inducing Group 3 medulloblastoma metastasis." (PMID 30297829, 2018). "Further genetic knockdown experiments are required to elucidate how TWIST1 is regulating ABCB1 and whether dual TWIST1/ABCB1 inhibition has the potential to prevent medulloblastoma metastasis." (PMID 33948561, 2021).
renal carcinoma (5 papers, 2015 to 2025). A carcinoma arising from the epithelium of the renal parenchyma or the renal pelvis. "Among different subgroups in renal cancer scRNAseq data, significant correlations between EMP1/COL3A1 and four EMT genes (VIM, SNAI2, TWIST1, and CTNNB1) were found in c9 fibroblasts." (PMID 38187400, 2023). "HSP90 interacts with its client protein STAT3 and facilitates the binding of STAT3 to the TWIST1 promoter, leading to the transactivation of TWIST1 and EMT induction in ovarian and renal cancer cells." (PMID 32151082, 2020).
tongue squamous cell carcinoma (5 papers, 2014 to 2021). A squamous cell carcinoma that arises from the tongue. "Another study suggested that miR-181a reversed chemoresistance due to down-regulation of Twist1 in tongue squamous cell carcinoma." (PMID 25760076, 2015). "Up-regulation of miR-181a reversed chemoresistance by targeting Twist1 in tongue squamous cell carcinoma." (PMID 24788655, 2014). "In addition, miR-23a promoted cisplatin chemo-resistance and protected cisplatin-induced apoptosis through induction of Twist1 expression via a JNK-dependent mechanism in tongue squamous cell carcinoma cells." (PMID 28099910, 2017). "Additionally, miR-181a modulated EMT and metastatic potential through targeting Twist1 in tongue squamous cell carcinoma." (PMID 25760076, 2015).
benign papilloma (4 papers, 2017 to 2026). "Twist-related protein 1 (TWIST1) is highly expressed in CP papillomas and involved in cell proliferation and invasion." (PMID 32375819, 2020). "Deletion of Twist1 in papillomas caused tumor regression without impacting markers of EMT, suggesting that Twist1 is necessary for tumor maintenance independent of EMT." (PMID 35892887, 2022).
colon adenocarcinoma (4 papers, 2017 to 2024). "The purpose of the current study is to assess the expression of MACC1, CD44, Twist1, and KiSS-1 in the colonic adenocarcinoma (CAC) tissues of patients and their associations between pathological characteristics and prognosis of patients with CAC." (PMID 30021598, 2018). "However, the associations of MACC1, CD44, Twist1, and KiSS-1 in colonic adenocarcinoma (CAC) invasion and metastasis remain unclear." (PMID 30021598, 2018). "In this regard, Twist1 (a major EMT inducer) significantly increases in vincristine-resistant human colon adenocarcinoma cells." (PMID 29271928, 2017). "Interestingly, Twist1-silencing reverses the EMT phenotype and enhances the chemo-sensitivity to anticancer agents including vincristine suggesting that EMT promotes the vincristine resistance of colon adenocarcinoma cells through Twist1." (PMID 29271928, 2017). "Studies showed that overexpression of MACC1, CD44, Twist1, and LNM and TNM stages were independent predictors of prognosis in patients with colonic adenocarcinoma." (PMID 39695175, 2024). "A cluster of 13 CpG loci (11 genes) were identified that displayed differential methylation in colon adenocarcinoma (COAD) (N = 289) compared to normal colon tissues (N = 38): ZNF671, TWIST1 (two CpG loci), TMEFF2, TM6SF1, GAS7, MAL, HIN1 (two CpG loci; SCGB3A1), COL6A2, AKR1B1, GPX7, ARHGEF7)." (PMID 34903270, 2021).
diabetes (4 papers, 2018 to 2023). "Loss of Akt2 also inhibited diabetes-induced elevation of RNA and protein levels of the EMT markers Snail/Slug and Twist1 in the RPE as compared to Akt2fl/fl diabetic mice." (PMID 37443129, 2023).
fibrosis (4 papers, 2024 to 2025). the formation of excess fibrous connective tissue in an organ or tissue in a reparative or reactive process. "In the skin and other fibrotic tissues, TWIST1 has been shown to induce the EMT, activate fibroblasts, and promote collagen deposition, reinforcing its central role in EMT-associated fibrosis." (PMID 40565255, 2025). "Consistently, our study showed that harmine administration or TWIST1 deletion relieved ECM deposition in mice exposed to chronic DSS-induced fibrosis." (PMID 39024569, 2024). "In these paths, the IPF node is directly connected to either EMT pathway nodes (SNAI2, TWIST1 and ZEB1) or dinoprostone (a pulmonary fibrosis regulator that expresses β-catenin), which is linked to CTNNB1." (PMID 38349059, 2024). "In addition, H&E and Masson staining revealed that Twist1 overexpression accelerated skin flap fibrosis and inhibited angiogenesis." (PMID 39474980, 2024).
idiopathic pulmonary fibrosis (4 papers, 2013 to 2023). Idiopathic pulmonary fibrosis (IPF) is a nonneoplastic pulmonary disease that is characterized by the formation of scar tissue within the lungs in the absence of any known cause. "Matrix metalloproteinase (MMP) 7, osteopontin, Twist1, and MMP19, are among suggested mediators identified using this strategy in idiopathic pulmonary fibrosis (IPF), a disease characterised by a histological pattern of usual interstitial pneumonia (UIP)." (PMID 23915349, 2013).
invasive ductal carcinoma (4 papers, 2012 to 2022). "Among the 58 invasive ductal carcinoma specimens, nearly half of the samples (44.8%, 26/58) displayed a reduced SPOP expression along with increased TWIST1, whereas one-third (32.8%, 19/58) of tumors with higher SPOP had lower TWIST1 and 12.1% of tumors had no changes in either one." (PMID 36115849, 2022). "Initially, the expression of TWIST1, SLUG, and SIP1 was evaluated individually and compared to patient data from the Brazilian National Cancer Institute cohort, which is a strictly selected cohort of invasive ductal carcinoma (IDC) containing all the relevant clinicopathological information." (PMID 34830027, 2021).
malignant glioma (4 papers, 2014 to 2023). A grade III or grade IV glioma arising from the central nervous system. "EMT-like changes in malignant gliomas are attributed to TWIST1, ZEB1/ZEB2 and SNAIl1/SNAIl2 as inducers for cell-invasiveness in GBMs." (PMID 24475040, 2014). "The current research has shown EMT-like changes in malignant gliomas, including a role for SNAIL1/SNAIL2, TWIST1/ TWIST2, ZEB1/ZEB2 and miRNAs as inducers for a cell-invasive phenotype in GBMs." (PMID 26761212, 2016).
meningioma (4 papers, 2011 to 2022). A generally slow growing tumor attached to the dura mater. "TWIST1 was slightly more prevalent in grade II, while SNAIL and SLUG were much stronger and frequent in grade II tumors, indicating their association to meningioma progression." (PMID 35163107, 2022). "Similarly, the roles of RUNX1, STAT5, and TWIST1 in meningioma remain poorly understood, and could represent novel therapeutic targets." (PMID 33093491, 2020). "In meningioma, transcription factors SNAIL, SLUG, and TWIST1 demonstrated strong expression in relation to E- and N-cadherin." (PMID 33915799, 2021). "The aim of our study was to investigate the involvement of main actors of the Wnt signaling pathway (β-catenin) and EMT (E-cadherin, N-cadherin, TWIST1, SNAIL and SLUG) in the progression of meningioma to its invasive grade." (PMID 33915799, 2021). "However, we showed extremely strong expressions of SNAIL, SLUG and TWIST1 in relation to the low expression of E-cadherin so their regulatory role in meningioma cannot be ruled out." (PMID 33915799, 2021).
pancreatic ductal adenocarcinoma (4 papers, 2017 to 2022). An infiltrating adenocarcinoma that arises from the epithelial cells of the pancreas. "In a similar line of study, Twist1 overexpression has shown to be associated with the progression of several human malignant tumors, including pancreatic ductal adenocarcinoma (PDAC)." (PMID 32655411, 2020). "Intriguingly, muscle Twist1 expression is highly induced in cachectic muscles from several mouse models of pancreatic ductal adenocarcinoma (PDAC), raising the interesting possibility that Twist1 may mediate PDAC-driven muscle cachexia." (PMID 32655411, 2020). "Besides, the association between Twist1 and another binding partner TGIF1 is able to inhibit Twist1, whereas this inhibitory effect can be abolished by the phosphorylation of TGIF1 in pancreatic ductal adenocarcinoma." (PMID 35601657, 2022).
cardiac hypertrophy (3 papers, 2012 to 2024). "Up-regulated genes bound by TWIST1 included the two pore channel Tpcn1; the Rho activating protein, Abra, which has been implicated in cardiac hypertrophy; the kinase Sik1; and the uncharacterized genes Gatsl2 and Wdr75." (PMID 22815831, 2012).
cholangiocarcinoma (3 papers, 2020 to 2023). A carcinoma that arises from the intrahepatic biliary tree (intrahepatic cholangiocarcinoma) or from the junction, or adjacent to the junction, of the right and left hepatic ducts (hilar cholangiocarcinoma). "Researches have shown that TWIST1 dependent VEGFC expression promoted the progression of cholangiocarcinoma." (PMID 35152264, 2022). "The miR-186 inhibits cell proliferation, migration, invasion, and EMT by targeting Twist1 in cholangiocarcinoma." (PMID 33381597, 2020).
Crouzon syndrome (3 papers, 2021 to 2025). Crouzon disease is characterized by craniosynostosis and facial hypoplasia. "We further detected low-grade mosaicism for a variant in the FGFR2 gene in a healthy parent of two children with Crouzon syndrome and for a deletion (including the TWIST1 gene) in a healthy father of a child with Saethre–Chotzen syndrome." (PMID 33288889, 2021).
developmental delay (3 papers, 2017 to 2025). "In affected individuals with major deletions involving other genes besides TWIST1, developmental delay and variable organ malformations (including anal stenosis and another ARM) have been described." (PMID 40225364, 2025). "Only a minority of the TWIST1+/− patients show signs of developmental delay and intellectual disability like those observed for the patient described in this study." (PMID 28126037, 2017).
endothelial dysfunction (3 papers, 2020 to 2025). In vascular diseases, endothelial dysfunction is a systemic pathological state of the endothelium (the inner lining of blood vessels) and can be broadly defined as an imbalance between vasodilating and vasoconstricting substances produced by (or acting on) the endothelium. "Though we focus on the role of TWIST1 in SMCs for these reasons, TWIST1 has been implicated in shear stress induced endothelial dysfunction and plays an important role in endothelial biology." (PMID 31917787, 2020). "The expression of the genes encoding EndoMT transcription factors (SNAI1, SNAI2, TWIST1, and ZEB1), which are generally upregulated at endothelial dysfunction, also showed ≥2-fold increase after PA-BSA treatment, in particular the TWIST1 (≈eight-fold increase) and SNAI1 genes (≈four-fold increase)." (PMID 41465574, 2025).
Hypertension (3 papers, 2022 to 2025). The presence of chronic increased pressure in the systemic arterial system. "This unexpected and completely novel link between TWIST1 and angiotensin-Rho/ROCK signaling is intriguing given that the 7p21.1 locus that modulates TWIST1 expression is also highly associated with hypertension in GWAS." (PMID 41246007, 2025). "Specifically, genetically-mediated increases in TWIST1 expression are associated with increased risk of hypertension." (PMID 41246007, 2025). "The convergence of two hypertension GWAS genes on a common pathway underscores the importance of this pathway and of understanding the precise mechanism by which TWIST1 modulates it." (PMID 41246007, 2025). "Sun, Yi’s team has demonstrated through animal experiments that TWIST1 in macrophages plays a critical role in mediating foam cell formation and increasing the vulnerability of atherosclerotic plaque during hypertension." (PMID 40109339, 2025). "TGF-β1 also stimulates the expression of TWIST1, and C3 stimulates the expression of renin to induce hypertension." (PMID 36018840, 2022). "It is thought that TWIST1 upregulates C3 to induce the EMT phenomenon that activates the intrarenal renin-angiotensin system and is associated the pathogenesis of hypertension." (PMID 36018840, 2022).